TNF (tumor necrosis factor)
Diseases named in the same sentence as TNF in open-access papers (continued):
Sharing a sentence is not in itself a finding about the gene and the disease.
Crohn disease (continued). "Recombinant leptin exerts diverse pro-inflammatory effects on immune cell differentiation and function, including the metabolic reprogramming of immune cells and the induction of TNFα, ultimately aggravating Crohn’s disease, which can be reversed by anti-TNFα therapy." (PMID 33921758, 2021). "Similarly, in inflamed mucosa of Crohn’s disease patients, the increase in XO, Mn-SOD activity, iNOS, and tumor necrosis factor-α (TNF-α) resulted associated with decreased antioxidant levels." (PMID 33573222, 2021). "Indeed, mice fed with high-fat diet increased TNF-α mRNA expression in the intestine, while patients with Crohn’s disease receiving anti-TNF-α treatment improves gut barrier function." (PMID 33810512, 2021). "A recent study showed that LrB could reduce the severity of inflammation in Crohn’s disease via inhibiting the expression levels of inflammatory cytokines interleukin-1 (IL-1), IL-6, and tumor necrosis factor-alpha (TNF-α)." (PMID 34248635, 2021). "Therefore, transmural and mucous healing was assessed by ultrasound, MRI, and colonoscopy in patients with Crohn’s disease during 2 years of anti-TNF α biological therapy." (PMID 34377195, 2021). "Response to anti-TNF therapy is of pivotal importance in patients with Crohn’s disease (CD)." (PMID 33750834, 2021). "Specifically, the biosimilar, infliximab-abda, became the preferred anti-TNF therapy for the treatment of immune-mediated inflammatory disorders, including ulcerative colitis and Crohn’s disease at the Cleveland Clinic and affiliated hospitals and health centers." (PMID 36777069, 2021). "Anti-TNF therapy was associated with a lower likelihood of mortality for Crohn disease but not ulcerative colitis." (PMID 33646314, 2021). "This study may provide additional evidence regarding potential non-invasive tools such as microbiota-based biomarkers of the response before and after anti-TNF therapy in Crohn’s disease as a starting point for future clinical trials." (PMID 32679874, 2020). "Discussion: In this study, massive sequencing, a reliable new tool, will be applied to identify early biomarkers of response to anti-TNF treatment in patients with Crohn’s disease to improve clinical management of these patients, reduce morbidity rates and improve efficiency." (PMID 32679874, 2020). "The cytokine TNF drives inflammatory diseases, e.g., Crohn's disease." (PMID 32914580, 2020). "Thetanix (gastroresistant capsules containing lyophilized Bacteroides thetaiotaomicron) is a live biotherapeutic, under development for Crohn's disease, that antagonizes transcription factor nuclear factor kappa B, reducing proinflammatory cytokines, particularly tumor necrosis factor alpha." (PMID 33464732, 2020). "Interestingly, the same allele is strongly associated with the risk of ADA against the widely used anti-tumor necrosis factor (TNF) treatments for Crohn’s disease." (PMID 33143745, 2020). "Considering the importance of Paneth cells in producing anti-microbial peptides and innate immune responses in the intestine, TNF mediated Paneth cell death may play an important role in the pathogenesis of Crohn’s disease." (PMID 32671059, 2020). "For example, Ruminococcus gnavus, a common gut pathogen in Crohn’s disease patients, utilizes mucin as a carbon source, directly breaking down the gut mucosal barrier and producing proinflammatory cytokines, including Tumor necrosis factor (TNF)-α." (PMID 33153085, 2020). "Therefore, we examined the criterion validity and responsiveness of these instruments in patients with Crohn’s disease who start tumor necrosis factor (TNF) inhibitors or corticosteroid treatment (treatments of known efficacy) for active disease." (PMID 31651651, 2020). "The increase in inflammatory cytokines, such as TNF-α, that occurs in Crohn’s disease may impact the integrity of epithelial cells and TJs." (PMID 33172188, 2020).
Crohn disease (continued). "Interestingly, patients with Crohn's disease on anti-TNFα antibody therapy showed increase in Roseburia abundance." (PMID 33194798, 2020). "miRNAs have been shown to regulate specific genes associated with Crohn’s disease (CD) including nucleotide-binding oligomerization domain-containing protein 2 (NOD2), IL-6, and tumor necrosis factor (TNF), but further studies are needed to clarify their precise role and their use in IBD management." (PMID 33138015, 2020). "Moreover, it was reported that paradoxical inflammations such as psoriasiform lesions, arthritis are induced by anti-TNF Mabs in some patients with Crohn’s disease and ulcerative colitis." (PMID 33193322, 2020). "Anti‐tumor necrosis factor alpha (TNF‐α) therapy is an effective therapy for Crohn's disease (CD)." (PMID 32514440, 2020). "Thus, the aim of the present research was to identify possible factors related toloss of response to anti-TNF agents in Crohn’s disease patients." (PMID 33237166, 2020). "However, therapeutic strategies to block TNFα to prevent fibrostenosis in Crohn’s disease have only been successful in animal models." (PMID 32528066, 2020). "Since administration of zinc and GCs together has such strong effects against TNF‐induced lethality, this combination may be of utmost benefit for treating intestinal pathologies involving TNF, such as Crohn's disease." (PMID 32914580, 2020). "Low trough levels at the time of anti-TNF discontinuation were associated with a lower relapse risk in Crohn’s disease patients but not in UC patients." (PMID 33154436, 2020). "Interestingly, hepcidin was found to be decreased in patients with Crohn's disease after successful therapy with anti-TNF-α mAb (i.e., infliximab), indicating the underlying association between TNF-α and hepcidin expression." (PMID 31814801, 2019). "Several recent studies suggested that TNF blocking agents are effective in Crohn's disease." (PMID 31737635, 2019). "However, only ~50% of Crohn's Disease patients achieve clinical remission with the anti-TNFα Humira® or Remicade®." (PMID 31396220, 2019). "Based on the original observation of an elevated expression of IL-26 in Crohn's disease, the authors reported that IL-26 induces the expression of the pro-inflammatory cytokines IL-8 and TNFα as well as the regulatory cytokine IL-10 in human gut epithelial cells." (PMID 30809226, 2019). "Mice rendered genetically deficient in SALSA have increased expression of inflammatory cytokines such as TNF, IL6, and NOD, and humans naturally deficient in SALSA are at increased risk of developing Crohn's disease, further suggesting that SALSA functions to dampening inflammation." (PMID 31850379, 2019). "Importantly, TNF can also initiate necroptosis and this is a common feature in the pathology of several inflammatory diseases and autoimmunity such as in Crohn’s disease (CD)." (PMID 29751683, 2018). "Moreover, a recent study has shown that low concentrations of F. prausnitzii are correlated with early recurrence of Crohn’s disease after anti-TNF-α treatment interruption." (PMID 29615661, 2018). "Overt fibrostenotic disease is a relative contraindication for anti-TNF therapy in Crohn’s disease." (PMID 29364909, 2018). "Besides, TNF-α is an important cytokine, which is reported to be implicated in both COPD and Crohn's disease (CD)." (PMID 29483875, 2018). "Physicians were surveyed about anti-TNF use in Crohn's disease (CD) and ulcerative colitis (UC)." (PMID 30009157, 2018). "Importantly, in human organoids from both healthy individuals and Crohn disease patients, overexpression of hLRH-1 abrogated TNFα-induced cell death." (PMID 30305617, 2018). "Marketing of TNF inhibitors revolutionized the treatment of diseases such as Crohn’s disease." (PMID 29751683, 2018). "White adipose tissue is known to synthesise PPAR-γ and TNF-α, and release cytokines including adiponectin and IL-642,43, hence may play a role in inflammatory response in Crohn’s disease." (PMID 30135522, 2018).
Crohn disease (continued). "Despite the paradigm shift seen over the last two decades with anti-TNF treatment in Crohn’s disease, the response that an individual patient will have to a specific anti-TNF and dose is difficult to predict when compared with conventional (non-biologic) therapies." (PMID 30065229, 2018). "One study in patients with Crohn disease revealed that TNF-α blockade (infliximab) could directly attenuate post-stimulated T cell CD154 expression in vitro and promote T cell apoptosis." (PMID 28837666, 2017). "Antitumour necrosis factor (anti-TNFα) agents, including infliximab (Remicade, Merck Sharp & Dohme) and adalimumab (Humira, AbbVie), are well-established second-line or third-line therapies for people with Crohn’s disease (CD)." (PMID 28674134, 2017). "Moreover, butyrate decreases the intestinal expression levels of tumor necrosis factor-α, IL-1b, and IL-6 in patients with Crohn’s disease." (PMID 28904265, 2017). "Although early treatment of Crohn’s disease (CD) patients with anti-tumor necrosis factor (TNF) agents or immunomodulators (IMs) may improve long-term outcomes, especially those with poor prognostic factors, their effectiveness in Asians remains unclear." (PMID 28542298, 2017). "Excessive TNF-α production could directly mediate or exacerbate several inflammatory diseases including Crohn’s disease, rheumatoid arthritis, and asthma." (PMID 29344411, 2017). "In Crohn’s disease anti-TNF biologics, packed red blood cells and antifungals are the three most expensive medications, while in ulcerative colitis antifungals, platelets and anti-TNF biologics lead (detailed data on file)." (PMID 26784027, 2016). "MH induction-effects by the current systemic drugs are not always satisfied, for example, anti-tumor necrosis factor (TNF) agents alone can achieve only 30.1% MH in Crohn’s disease (CD) and approximately 60% MH at week 8 in ulcerative colitis (UC), in spite of their primary usage." (PMID 27410685, 2016). "Interestingly, anti-TNF therapy successfully improved anemia in clinical responsive Crohn’s disease patients, and DMT1 was found to be markedly up-regulated in intestinal mucosa." (PMID 26572590, 2015). "Furthermore, patients with Crohn’s disease displayed slightly decreased proportions of FOXP3ex6/8 when successfully treated with anti-TNF-α antibodies." (PMID 26441347, 2015). "The use of pharmacokinetics is associated with cost savings in anti-tumor necrosis factor (anti-TNF) therapy, but the long-term cost savings in a large cohort of Crohn's disease (CD) patients are unknown." (PMID 27123185, 2015). "Studies in humans with other forms of GI disease such as Crohn’s disease (CD) have suggested that aberrant handling of luminal bacteria by the innate immune system results in an activated inflammatory cascade and secretion of cytokines (i.e., TNF-α and IFN-γ)." (PMID 26000959, 2015). "Interestingly, anecdotal evidence suggests positive effect of anti-TNF-α treatment in Crohn's disease on AN." (PMID 25147950, 2014). "Sarcoidosis may occur during anti-TNFα treatment of Crohn's disease and other inflammatory and rheumatic diseases and with other drugs interfering with the cell interaction processes." (PMID 24653848, 2014). "In addition, since tumor necrosis factor-α (TNF-α) plays a central role in the pathogenesis of Crohn's disease, use of biologic agents, such as monoclonal antibodies inhibiting TNF-α, has proven to be effective for this disorder." (PMID 24872818, 2014). "A 42-year-old man presented with an 11-year-long history of Crohn's disease; upon discovery of an abnormal chest CT scan the diagnosis of multivisceral sarcoidosis was made and, later, a treatment with an anti-TNFα agent, infliximab, was started, because of worsening Crohn's disease recurrences." (PMID 24653848, 2014).
Crohn disease (continued). "TNF-α is an attractive target for the development of anti-inflammatory drugs because it is an important mediator in the pathogenesis of several inflammatory diseases, including RA, Crohn ̓s disease and ankylosing spondylitis." (PMID 24896264, 2014). "Short- and long-term anti-TNF-α therapies in Crohn's disease are generally well tolerated." (PMID 25374717, 2013). "Infliximab has been thought to exert its biological functions through blocking TNF, while a recent study found that IL-15 and its soluble receptor might mediate the response to infliximab in patients with Crohn's disease." (PMID 23484133, 2013). "Moreover, L. monocytogenes and E. coli infection are a side-effect of anti-TNFα therapy in Crohns disease." (PMID 24058654, 2013). "Anti-TNF-α treatment improves gut barrier function in patients with Crohn's disease." (PMID 22457829, 2012). "Another study suggested suppression of TNF-α and IL-12 as a possible mechanism of thalidomide's clinical effects in Crohn's disease, which improves clinical symptoms in patients, what may explain its clinical efficacy." (PMID 21276247, 2011). "In Crohn's disease TNF concentration is abnormally high in serum as well as in the gut mucosa." (PMID 22074550, 2011). "There was growing evidence that the efficacy of anti-TNFα therapies in Crohn's disease may critically depend on the affinity of TNFα antagonists to TNFα." (PMID 20140191, 2010). "Both of these anti-TNF drugs appear to be equally efficacious in the treatment of Crohn's Disease and therefore the decision regarding which drug to choose will depend to some extent on patient choice, which may be based on the mode of administration." (PMID 20064220, 2010). "Therefore, the current recommendation for the discontinuation of TNF-α inhibitors in patients with Crohn's disease during the treatment of active tuberculosis should be re-evaluated." (PMID 19830122, 2009). "TNFα plays a pivotal role in the pathogenesis of IBDs including Crohn's disease." (PMID 17078892, 2006). "These investigators hypothesize that this may have resulted from decreased tumor necrosis factor-alpha (TNFα), which is known to play a vital role in Crohn's disease." (PMID 16984660, 2006). "Crohn's disease (CD) and eosinophilic gastrointestinal diseases (EGIDs) are distinct inflammatory entities, but eosinophilic disease may emerge as a paradoxical immune complication of anti-tumor necrosis factor therapy." (PMID 42110122, 2026). "TNF-α inhibitors, used for the treatment of inflammatory autoimmune diseases, for instance, in RA, ankylosing spondylitis, Crohn’s disease, inflammatory bowel disease, Behcet’s disease, psoriasis, psoriatic arthritis, and juvenile arthritis, may exacerbate MRONJ." (PMID 40709114, 2025). "Indeed, network meta-analyses confirm the high efficacy of anti-TNF-α agents in challenging clinical settings scenarios, such as preventing recurrence in Crohn’s disease, which underscores the urgent need for alternatives that can circumvent overcome these drawbacks." (PMID 41296400, 2025). "Thus, individuals with severe Crohn’s disease, for example, may start first-line therapy using anti TNF monoclonal antibodies, given proven efficacy for such scenarios." (PMID 41398905, 2025). "Moreover, IL23R+ intestinal T-cell populations expand in Crohn’s disease and associate with anti-TNF non-response." (PMID 41154835, 2025). "In Crohn’s disease (CD) patients who have undergone surgery, postoperative recurrence remains a challenge, and there is a lack of investigation into the impact of early anti-tumor necrosis factor (TNF) therapy following surgery on clinical outcomes compared to late use of anti-TNF agents." (PMID 40216839, 2025).
Crohn disease (continued). "Notably, the FDA approved upadacitinib as the first oral treatment option for Crohn’s disease in patients with inadequate response or intolerance to tumor necrosis factor (TNF) blockers, highlighting its growing role in addressing unmet clinical needs across multiple inflammatory conditions." (PMID 41404585, 2025). "Anti-TNF therapy resulted in a greater reduction in aphthous ulceration in both Crohn's disease and UC than anti-integrin therapy, but it was acknowledged that this may reflect a more severe disease phenotype in the anti-integrin cohort, as these are generally second line agents." (PMID 38388611, 2024). "In fact, Crohn's disease patients are 5–10 times more likely to receive anti-tumor necrosis factor-α (TNF-α) treatment than ulcerative colitis patients, which could be a key influencing factor leading to differing results between previous studies and our findings." (PMID 38343642, 2024). "The use of concomitant medications for Crohn’s disease was similar between the treatment groups, with 30% of patients using corticosteroids at baseline and 50% of patients using concomitant immunomodulators, including 24% of patients using concomitant anti-TNF agents." (PMID 39199994, 2024). "This study tested whether the addition of anti-MAP antimicrobial therapy (RHB-104) to standard-of-care therapy, including immunosuppressive therapy with TNF inhibitors, was superior to placebo plus standard-of-care for the therapy of patients with moderately to severely active Crohn’s disease." (PMID 39199994, 2024). "Furthermore, polymorphisms in receptors downstream of TNF-α signaling are also associated with dysregulated inflammation, such as RA, Crohn’s disease, AS, and graft-versus-host disease, which alter binding kinetics between TNFR2 and TNF-α and, hence, the frequency of TNF signal transduction." (PMID 36835647, 2023). "Fractalkine expression is upregulated by inflammatory cytokines (IFN-γ, IL-1β and TNF-α) or by direct leukocyte contact, and has been detected in intestinal epithelial cells and endothelial cells both in normal small intestine and in active Crohn’s disease mucosa." (PMID 37645250, 2023). "Enhanced systemic TNF-α levels in subjects with single-IgG2 coated bacteria, and increased prevalence in Crohn’s disease patients with active disease, further substantiate that single-IgG2 coating is linked to local and systemic inflammation, and may be a marker for on-going inflammatory processes." (PMID 38065985, 2023). "Furthermore, inflammatory monocytes in ulcerative colitis and Crohn’s disease express TNF but may also aid in anti-TNF therapy resistance." (PMID 35440548, 2022). "However, post-hoc analysis using Bonferroni correction indicated that TNF-antagonist treatment significantly increased the risk of ulcerative colitis (p < 0.0001), but not Crohn’s disease (p = n.s)." (PMID 35440548, 2022). "While TNF-antagonists are currently used to treat a number of AI conditions, a limited number of studies have suggested that treatment with these drugs can actually increase incidence of a subset of AI conditions, including Crohn’s disease and ulcerative colitis." (PMID 35440548, 2022). "Several studies have found that the levels of TNF and IL-6 are increased in the serum and the intestinal mucosa of patients with active Crohn’s disease, and are positively correlated with the clinical disease activity and histopathological signs of inflammation in Crohn’s disease patients." (PMID 36139127, 2022). "In this comparative effectiveness study of older patients with IBD, vedolizumab was associated with a higher risk of treatment failure compared with TNF antagonists, particularly among patients with Crohn disease, without offering a significant safety advantage." (PMID 36178685, 2022).